CTH (cystathionine gamma-lyase)
Diseases named in the same sentence as CTH in open-access papers (continued):
Sharing a sentence is not in itself a finding about the gene and the disease.
atherosclerosis (5 papers, 2019 to 2025). A disease characterized by the build-up of fatty material and calcium deposition in the arterial wall resulting in partial or complete occlusion of the arterial lumen. "VSCMs produce CTH-H2S (cystathionine gamma-lyase-hydrogen sulfide), which has a protective role in atherosclerosis and whose levels are decreased in atheromas in comparison with the healthy vascular wall." (PMID 38673936, 2024). "In the macrophages of ox-LDL-treated apoE−/− mice, the upregulation of DNMTs was associated with DNA hypermethylation in the cystathionine-gamma-lyase (CSE) gene promoter, which resulted in the inflammation of macrophages and the acceleration of atherosclerosis." (PMID 30857550, 2019). "Vascular smooth muscle cells (VSMCs) are significant contributors to plaque stability, partly through the production of cystathionine gamma-lyase (CTH), which generates hydrogen sulfide (H2S), a protective gasotransmitter in atherosclerosis." (PMID 40426881, 2025). "Although prior studies have implicated SENP3 in cancer and metabolic cardiovascular diseases through substrates such as β-catenin, YAP1 and CTH, its role in atherosclerosis has not been explored." (PMID 41307849, 2025). "Although SENP3 has been implicated in cancer and metabolic disease through its deSUMOylation of substrates such as β-catenin, YAP1 and CTH, its potential role in atherosclerosis and VSMC phenotypic modulation has not been examined." (PMID 41307849, 2025).
glioma (5 papers, 2019 to 2025). A benign or malignant brain and spinal cord tumor that arises from glial cells (astrocytes, oligodendrocytes, ependymal cells). "•CTH is upregulated in human gliomas and associated with worse overall survival." (PMID 37300955, 2023). "A recent study analyzing the impact of antioxidant GSH in specific subtypes of gliomas, indicated the importance of CTH as precursor enzyme for high GSH synthesis in astrocytoma cells." (PMID 37300955, 2023). "Bioinformatic analysis in human glioma tumors revealed that higher CTH expression is positively correlated to SOX2 expression and associated with worse overall survival in all grades of gliomas." (PMID 37300955, 2023). "Moreover, high CTH expression led to a clear trend with almost acceptable significance (P-value: 0.056) for lower survival probability in recurrent gliomas of all grades." (PMID 37300955, 2023). "Indeed, our bioinformatic analysis suggests that CTH is overexpressed in human GBM tumors and higher CTH expression is significantly correlated with lower survival probability in all grades of primary gliomas." (PMID 37300955, 2023). "In human gliomas, the CTH expression was analyzed by bioinformatic analysis on different databases." (PMID 37300955, 2023). "This phenomenon was attributed to the lower expression of PHGDH and CTH, enzymes involved in serine and cystathionine metabolism, in gliomas with chromosomal alterations compared to those without them." (PMID 39996200, 2025). "By analyzing the CTH mRNA expression profile on the CGGA database, we found that higher CTH expression is correlated with significantly worse survival probability in all primary gliomas of different grades." (PMID 37300955, 2023). "Based on bioinformatic analysis on ‘The Cancer Genome Atlas’, TCGA, we found a significant upregulation of CTH mRNA expression in all grades of human gliomas compared to healthy/non-tumoral brain tissue." (PMID 37300955, 2023). "Concordantly, the association between CTH expression and poor survival was also observed in pancreatic adenocarcinoma (PAAD) and lower grade glioma (LGG) from the TCGA RNA‐seq datasets (Fig EV1G and H), implying that CTH may play a crucial role during cancer progression in various cancer types." (PMID 31468690, 2019).
hepatocellular carcinoma (5 papers, 2020 to 2025). A malignant tumor that arises from hepatocytes. "FOXC1 induces CTH promoter DNA hypermethylation through upregulation of DNMT3B to promote proliferation and metastasis in primary hepatocellular carcinoma." (PMID 34970791, 2022). "FOXC1 induced CTH promoter DNA hypermethylation through upregulation of DNMT3B to promote proliferation and metastasis in primary hepatocellular carcinoma." (PMID 34904288, 2022). "CBS (cystathionine beta-synthase) and CTH (cystathionine gamma-lyase) may generate cysteine via the transsulfuration pathway, but CBS or CTH inhibitors can trigger ferroptosis in hepatoma cells or NSC-34 motor neuron-like cells." (PMID 38213172, 2024). "Our analysis of The Cancer Genome Atlas (TCGA) human Liver Hepatocellular Carcinoma (LIHC) dataset confirmed that key genes involved in SAA metabolism, including MAT1A, BHMT, CBS, CTH, and CDO1, are suppressed in HCC compared to normal liver." (PMID 32770044, 2020).
lung carcinoma (4 papers, 2014 to 2024). "Importantly, overexpression of REV1 in USP9X-deficient lung cancer cells was able to reverse the upregulation of CTH expression." (PMID 38802791, 2024). "The expression of CTH was upregulated after knockdown of Rad18 in lung cancer cells, and Rad18 silencing resulted in reduced ubiquitination levels and prolonged protein half-life of CTH, suggesting that CTH is a substrate for the E3 ubiquitin ligase Rad18." (PMID 38802791, 2024). "Knockdown of Rad18 in three different lung cancer cells resulted in CTH upregulation, and treatment with MG132 significantly inhibited this observation." (PMID 38802791, 2024). "We first exogenously overexpressed REV1 in lung cancer cells and detected the downregulation of CTH expression." (PMID 38802791, 2024). "Importantly, the rescue assay revealed that CTH expression was downregulated in lung cancer cells overexpressing REV1." (PMID 38802791, 2024). "Aberrantly expressed REV1 acts as a scaffolding protein to assist the interaction between the Rad18 E3 ubiquitin ligase and CTH, promoting CTH ubiquitination-mediated degradation and inducing remodeling of the amino acid metabolic microenvironment, leading to lung cancer radioresistance." (PMID 38802791, 2024). "In this study, we report for the first time that the high REV1 expression in lung cancer is associated with the deubiquitinase USP9X and that abnormally high REV1 expression can act as a scaffolding protein to assist the E3 ubiquitin ligase Rad18 binding to the substrate CTH." (PMID 38802791, 2024). "This binding promotes the ubiquitin-mediated degradation of CTH, thereby increasing the intra- and extracellular levels of Gly/Ser/Thr and inducing the formation of an abnormal tumor metabolic microenvironment that ultimately renders lung cancer cells insensitive to radiotherapy." (PMID 38802791, 2024). "Notably, in lung cancer tissues, endogenous H2S and its producing enzymes, like cystathionine beta-synthase (CBS), cystathionine gamma lyase (CSE, also known as CTH) and 3-mercaptopyruvate sulfurtransferase (3-MST), are highly expressed thereby benefiting cancer development." (PMID 32195181, 2020).
preeclampsia (4 papers, 2019 to 2025). Preeclampsia is a hypertensive disorder of pregnancy that is characterized by new-onset hypertension with proteinuria presenting after 20 weeks of gestation, and depending on mild or severe forms may initially present with severe headache, visual disturbances, and hyperreflexia. "The discovery that miR-30b modulates the CTH/MMP-TIMP axis in preeclampsia has significant clinical implications." (PMID 40013213, 2025). "In women with preeclampsia, the expression of hydrogen sulfide producing enzyme, cystathionine gamma-lyase (CSE) is decreased in the placenta and so is the levels of hydrogen sulfide (H2S) in the maternal circulation." (PMID 33137710, 2021). "The use of miR-30b inhibitors in preeclampsia could restore CTH expression and H2S levels, promoting trophoblast invasion and reducing the risk of placental insufficiency." (PMID 40013213, 2025). "Emerging therapeutic strategies targeting oxidative stress, inflammation, angiogenesis, and specific molecular pathways like the heme oxygenase-1/carbon monoxide (HO-1/CO) and cystathionine gamma-lyase/hydrogen sulfide (CSE/H2S) pathways show promise in mitigating preeclampsia’s effects." (PMID 39062815, 2024). "As lactation failure can be managed in clinical settings, this study may help the understanding of the pathophysiology of preeclampsia in relationship to homocysteine and transsulfuration pathway mediated by CBS and CTH." (PMID 31319489, 2019).
Sepsis (4 papers, 2016 to 2023). Sepsis is defined as life-threatening organ dysfunction caused by a dysregulated host response to infection. "Hydrogen sulfide (H2S), synthesized by cystathionine gamma-lyase (Cth), contributes to the inflammatory response observed in sepsis." (PMID 37686458, 2023). "This suggest that the DG treatment may favorably impact the heart in a sepsis condition and that it could restore the redox homeostasis in part by the H2S, CBS, CTH, GSH, and thiol elevations in this organ." (PMID 36293383, 2022).
acute pancreatitis (3 papers, 2023 to 2024). An acute inflammatory process that leads to necrosis of the pancreatic parenchyma. "Silencing the CTH gene in monocytes using siRNA has been shown to protect mice from caerulein-induced acute pancreatitis and concurrent lung injury." (PMID 39062461, 2024). "Additionally, CTH gene silencing seemed to prevent the reduction in splenic monocyte numbers observed in the acute pancreatitis model, suggesting that the spleen may serve as a reservoir for monocytes during inflammation." (PMID 39062461, 2024).
Alzheimer disease (3 papers, 2019 to 2023). A progressive, neurodegenerative disease characterized by loss of function and death of nerve cells in several areas of the brain leading to loss of cognitive function such as memory and language. "H2S, as an endogenous molecule produced by the enzymatic activity of CTH, CBS, or MPST, is the main regulator of post-translational S-sulfhydration (persulfidation) of proteins that has been reported, e.g., in aging, Alzheimer’s disease, or the cardiovascular system." (PMID 37627540, 2023).
astrocytomas (3 papers, 2023 to 2025). "CTH was specifically up-regulated in IDH1-mutant astrocytomas to sustain de novo GSH production under cysteine restriction, and CTH inhibition with brain-penetrant propargylglycine impaired tumor growth in vivo." (PMID 41154707, 2025). "Concerning cystathionine gamma-lyase (CTH), a selective CTH inhibitor has been found to specifically target the active site, showing high sensitivity in IDH1 mutant astrocytomas." (PMID 38469348, 2024). "A study published last year showed that CTH is upregulated in IDH-1 mutant astrocytomas and pharmacological CTH inhibition could attenuate to some extent astrocytoma growth in immunodeficient mice." (PMID 37300955, 2023).
colorectal cancer (3 papers, 2018 to 2025). A primary or metastatic malignant neoplasm that affects the colon or rectum. "This is consistent with the mutations previously identified by our group in colorectal cancer patients (Housein, Kareem & Salihi, 2021), in which several NOS3 and CTH gene mutations were discovered." (PMID 38107574, 2023). "However, experimental studies are providing increasing support for a role of the two main transsulfuration pathway enzymes CBS and CTH in colorectal cancer development through production of the gasotransmitter hydrogen sulfide." (PMID 29694444, 2018).
lung adenocarcinoma (3 papers, 2016 to 2025). A carcinoma that arises from the lung and is characterized by the presence of malignant glandular epithelial cells. "This study aims to show the contribution and effects of various gene polymorphisms in the NOS3 and CTH genes, as well as their associations with lung adenocarcinoma." (PMID 38107574, 2023). "Here we show that human lung adenocarcinoma tissue expresses high levels of hydrogen sulfide (H2S) producing enzymes, namely, cystathionine beta-synthase (CBS), cystathionine gamma lyase (CSE) and 3-mercaptopyruvate sulfurtransferase (3-MST), in comparison to adjacent lung tissue." (PMID 27808278, 2016).
melanoma (3 papers, 2014 to 2023). A malignant, usually aggressive tumor composed of atypical, neoplastic melanocytes. "Overexpression of CTH in human melanoma cells induced apoptosis by suppressing the activity of nuclear factor-kB (NF-kB) and decreasing the expression of antiapoptotic proteins." (PMID 31861640, 2019). "In this research paper, we examined the expression levels of sulfurtransferases (MPST, TST, CTH) and cystathionine beta-synthase in human primary (WM115) and metastatic (WM266-4) melanoma cell lines both in normoxic and hypoxic conditions." (PMID 37892173, 2023). "Thus, it seems that MPST can play an important role in the progression of human melanoma cells (WM115 and WM266-4) compared to other sulfurtransferases such as TST and CTH, of which, expression in both cell lines was not changed." (PMID 37892173, 2023).
clear cell carcinoma (2 papers, 2016 to 2023). "A tissue microarray analysis validated cystathionine gamma-lyase (CTH) as a novel clear cell carcinoma feature with potential clinical relevance." (PMID 27713570, 2016).
Cognitive impairment (2 papers, 2017 to 2025). Abnormal cognition is characterized by deficits in thinking, reasoning, or remembering. "Our first finding reveals that early microvascular changes, including capillary stalling, increased CTH, and capillary morphometric alterations, coexist with Aβ accumulation before cognitive impairment." (PMID 40133235, 2025). "One explanation might be that CTH get altered in the later stages and/or more severe cases of cognitive impairment in LLD and that relevance of the structural brain measurement as a biomarker therefore depends on the stage of the disease." (PMID 28210220, 2017).
colitis (2 papers, 2023 to 2024). Inflammation of the colon. "In this context, the aim of the present paper was to determine the role of CTH in inflammation in the colon and, by extension, in colitis-associated carcinogenesis (CAC)." (PMID 39427081, 2024). "We observed that CTH is induced in the colon of mice with DSS colitis, as previously observed in rats." (PMID 39427081, 2024). "We found that DSS colitis was similar between WT and Slc7a11–/– mice, suggesting that the deleterious effect of CTH in our model occurs independently of intracellular cysteine level." (PMID 39427081, 2024). "First, we found that CTH is induced in the colon mucosa in mice with dextran sulfate sodium-induced colitis." (PMID 39427081, 2024). "In this context, it is probable that the deleterious effect of CTH on DSS colitis that we have observed has a multifactorial etiology." (PMID 39427081, 2024). "Interestingly, we observed that WT mice with DSS colitis have increased CTH expression in their colon, which can in turn lead to increased H2S generation." (PMID 39427081, 2024). "Loss of diversity is mainly associated with development of more severe colitis in mice and is a hallmark of IBD pathogenesis, suggesting that CTH may support colon inflammation by reducing diversity." (PMID 39427081, 2024). "Our present data showed an increased Firmicutes/Bacteroidetes ratio in Cth–/– mice, which are protected from DSS colitis, suggesting that CTH activity in the colon may sustain a pro-inflammatory microbiota through the dysbiosis of this ratio." (PMID 39427081, 2024). "Altogether, these data evidence that CTH supports the development of colitis in our DSS model." (PMID 39427081, 2024). "Therefore, we reasoned that one mechanism by which CTH could support DSS colitis might be by reducing intracellular cysteine." (PMID 39427081, 2024). "Treatment with a nonspecific CTH inhibitor propargylglycine exacerbated DSS-induced colitis in mice, and mRNA expression of three H2S-producing enzymes (CTH, MPST, and cystathionine β-synthase [CBS]) and H2S production was upregulated in the colon mucosa in the experimental colitis of mice/rats." (PMID 36768979, 2023).
Ewing sarcoma (2 papers, 2024). A small round cell tumor that lacks morphologic, immunohistochemical, and electron microscopic evidence of neuroectodermal differentiation. "Recent research highlights that IL1 receptor accessory proteins can mitigate apoptosis in Ewing's sarcoma by enhancing the activity of the Xc-cystine/glutamate antiporter and CTH transcription, thereby maintaining cysteine levels for reactive oxygen species detoxification." (PMID 38388661, 2024). "Interestingly, high CTH expression was found to be associated with shorter event-free survival in two separate cohorts of patients with Ewing sarcoma, supporting a role for CTH in Ewing sarcoma malignancy." (PMID 38334625, 2024).
gastric cancer (2 papers, 2021 to 2024). A primary or metastatic malignant neoplasm involving the stomach. "The dysregulation of Cystathionine Gamma-Lyase (CTH), Microtubule Associated Protein 1 Light Chain 3 Beta (MAP1LC3B), and monocyte-macrophage dynamics are critical determinants of the poor prognosis associated with gastric cancer (GC)." (PMID 38388661, 2024). "The differential enrichment patterns observed for CTH and MAP1LC3B suggest their unique contributions to the molecular dynamics of gastric cancer, potentially offering avenues for targeted therapeutic strategies." (PMID 38388661, 2024). "Cystathionine Gamma-Lyase (CTH) exhibited a significantly lower expression in this group (p < 0.001), suggesting its potential role as a protective factor in gastric cancer (GC) progression." (PMID 38388661, 2024).
leukemia (2 papers, 2022 to 2024). A malignant (clonal) hematologic disorder, involving hematopoietic stem cells and characterized by the presence of primitive or atypical myeloid or lymphoid cells in the bone marrow and the blood. "This is directly linked to disruptions in CTH gene expression, potentially causing leukemia cells to become cysteine auxotrophs." (PMID 39062461, 2024). "CTH activity in immune system cells is relatively low and further impaired in some leukemia cell lines." (PMID 39062461, 2024). "CTH expression was obtained in different leukemia cell lines, including REH, DND-41, MOLT-4 (ALL cell lines), MV4-11, MOLM-14 (AML cell line), and K562 (CML cell line)." (PMID 39062461, 2024). "It seeks to identify potential bottlenecks in sulfur metabolism in leukemia cells, concentrating on four key enzymes: TST, MPST, CTH, and CBS." (PMID 39062461, 2024). "Our results also showed that the expression of CTH was the highest in MOLM-14 and K562 cells as compared to the other studied leukemia cell lines." (PMID 35204649, 2022). "In the present paper, we investigated the expression of TST, MPST, CTH, and CBS in the different types of human leukemia cell lines: B-ALL (REH cells), T-ALL (DND-41 and MOLT-4 cells), AML (MV4-11 and MOLM-14 cells), and CML (K562 cells)." (PMID 35204649, 2022). "In different types of leukemia cell lines, such as REH, DND-41, MOLT-4, MV4-11, MOLM-14, and K562, gene expression for TST, MPST, CBS, and CTH was studied on the mRNA and protein level." (PMID 35204649, 2022). "In conclusion, our findings showed significant differences in the expression of TST, MPST, CTH, and CBS in different types of human leukemia cells." (PMID 35204649, 2022).
liver cancer (2 papers, 2021 to 2024). An epithelial or non-epithelial malignant neoplasm that arises from the liver. "X-rays activate the p38 mitogen-activated protein kinase, which in turn activates the CTH/H2S signaling pathway, inducing epithelial-mesenchymal transition and promoting invasion of liver cancer cells." (PMID 39010084, 2024). "Overexpression of CTH significantly inhibits the proliferation, invasion, and metastasis of liver cancer cells induced by FOXC1." (PMID 39010084, 2024). "Human Protein Atlas program database showed high or medium CTH staining intensity in normal liver samples, whereas liver cancer samples showed low staining of CTH by immunohistochemistry (IHC) tissue microarray data." (PMID 33522955, 2021).